PLPP2 (phospholipid phosphatase 2)
Description:
Magnesium-independent phospholipid phosphatase that catalyzes the dephosphorylation of a variety of glycerolipid and sphingolipid phosphate esters including phosphatidate/PA, lysophosphatidate/LPA, sphingosine 1-phosphate/S1P and ceramide 1-phosphate/C1P. Has no apparent extracellular phosphatase activity and therefore most probably acts intracellularly. Also acts on N-oleoyl ethanolamine phosphate/N-(9Z-octadecenoyl)-ethanolamine phosphate, a potential physiological compound. Through dephosphorylation of these bioactive lipid mediators produces new bioactive compounds and may regulate signal transduction in different cellular processes (Probable). Indirectly regulates, for instance, cell cycle G1/S phase transition through its phospholipid phosphatase activity (By similarity).
Synonyms: PAP2-G; PAP-2c; LPP2; PPAP2C
Tractability: Antibody: UniProt places it where antibodies can reach, with high confidence; its Gene Ontology location is reachable by antibodies, with high confidence; UniProt predicts a signal peptide or a membrane-spanning region; the Human Protein Atlas places it where antibodies can reach. PROTAC: ubiquitination databases record sites on it.
Gene: Protein-coding gene on chromosome 19 (278,504 to 291,403, reverse strand). Ensembl gene ENSG00000141934.
Subcellular location: Membrane; Cell membrane; Early endosome membrane; Endoplasmic reticulum membrane
Subcellular location (Human Protein Atlas): Plasma membrane
Pathways (Reactome):
Metabolism: Sphingolipid catabolism
Gene Ontology:
Molecular function: ceramide-1-phosphate phosphatase activity; phosphatidate phosphatase activity; protein binding; sphingosine-1-phosphate phosphatase activity
Biological process: ceramide metabolic process; phospholipid dephosphorylation; phospholipid metabolic process; sphingosine metabolic process; signal transduction; sphingolipid catabolic process
Cellular component: caveola; early endosome; early endosome membrane; endoplasmic reticulum; endoplasmic reticulum membrane; membrane; plasma membrane
Genetic constraint (gnomAD): Loss-of-function variants: 29 observed, 35.61 expected, observed/expected ratio (o/e) 0.81, 90% interval 0.61 to 1.11. The upper end of that interval is the gene's LOEUF score, 1.11, which puts it in group 4 of 6, group 1 being the genes least tolerant of losing a copy. Missense variants: 353 observed, 367.13 expected, observed/expected ratio (o/e) 0.96, 90% interval 0.88 to 1.05. Synonymous variants: 162 observed, 160.87 expected, observed/expected ratio (o/e) 1.01, 90% interval 0.88 to 1.15.
Homologues: Orthologues: chimpanzee PLPP2 (93% identical), dog PLPP2 (93% identical), pig PLPP2 (89% identical), mouse Plpp2 (86% identical), rabbit PLPP2 (84% identical), rat Plpp2 (84% identical), guinea pig PLPP2 (77% identical), tropical clawed frog plpp2 (73% identical), zebrafish plpp2a (66% identical), zebrafish plpp2b (62% identical), Caenorhabditis elegans plpp-1.1 (39% identical), Drosophila melanogaster wun (37% identical), and 7 more. Paralogues in human: PLPP1 (55% identical), PLPP3 (47% identical), PLPPR4 (27% identical), PLPPR3 (26% identical), PLPPR2 (25% identical), PLPPR1 (24% identical), PLPP5 (23% identical), PLPP4 (23% identical), PLPPR5 (22% identical).
Diseases named in the same sentence as PLPP2 in open-access papers:
PLPP2 is named in the same sentence as 24 diseases in open-access papers, as found by Europe PMC text mining. Sharing a sentence is not in itself a finding about the gene and the disease. The quoted sentences say what the papers report.
breast carcinoma (4 papers, 2019 to 2023). "Previous studies have demonstrated that PLPP2 could regulate tumor growth by modulating cell-cycle progression; knockdown of PLPP2 in breast cancer cells resulted in reduced c-myc expression and inhibition of G1 to S phase transition." (PMID 37996944, 2023). "In this study, we explore the role of LPP mRNA expression (LPP1 gene name PLPP1 and historically PAPP2A; LPP2 gene name PLPP2, PAPP2C; LPP3 gene name PLPP3, PAPP2B) within the human breast cancer TME via in silico research approaches using three large independent cohorts." (PMID 37190226, 2023). "Meanwhile, several other risk model genes were identified in this study (ST6GALNAC4, PLPP2, ELOVL1, HACD1, VAPB, CERS2, ALDH3B2, and HACD3) have not yet been explored in depth in breast cancer." (PMID 36059802, 2022).
lung adenocarcinoma (3 papers, 2017 to 2025). A carcinoma that arises from the lung and is characterized by the presence of malignant glandular epithelial cells. "Specifically, the development of phospholipid phosphatase 2 (PLPP2)-mediated lipid raft synthesis represents an important biological event in the early progression of lung adenocarcinoma, providing potential targets for more precise diagnosis and treatment in clinical settings." (PMID 40231255, 2025).
lung carcinoma (3 papers, 2017 to 2023). "Overall, our findings suggested that PLPP2 might enhance the survival of lung cancer cells by promoting proliferation and inhibiting cell death through enhancing lipid raft formation." (PMID 37996944, 2023).
Obesity (2 papers, 2009 to 2018). Accumulation of substantial excess body fat. "Obesity and other behavioral factors may also affect tumor microenvironment, and G6PD and PLPP2 were also overexpressed in normal tissues form patients with advanced stage ccRCC in the TCGA dataset." (PMID 30603059, 2018).
breast tumors (1 paper, 2021). "However, the expression of PLPP1 and PLPP2 was decreased and increased, respectively, in primary breast tumors compared to normal breast tissue." (PMID 34235182, 2021).
renal cell cancer (1 paper, 2023). "Conversely, elevated levels of PLPP2 have been observed in many cancers, including liver and prostate, breast and renal cell cancer, which was opposite to the expression pattern of PLPP1 and PLPP3." (PMID 37996944, 2023).
cancer (6 papers, 2015 to 2023). A tumor composed of atypical neoplastic, often pleomorphic cells that invade other tissues. "In vitro experiments had also shown that knockdown of PLPP2 weakened the growth of anchor-dependent cancer cell lines and reduced cell proliferation by delaying S-phase entry, unlike what was seen with PLPP1 and PLPP3." (PMID 37996944, 2023). "Moreover, it was reported that a series of in vitro data, including anchorage-dependent growth and proliferation assays, validated PLPP2 as a putative therapeutic target for treatment of cancer." (PMID 28851360, 2017).
tumor (4 papers, 2018 to 2024). "Subsequent in vivo and in vitro experiments provided further evidence supporting the role of PLPP2 in promoting cell proliferation and tumor growth through its influence on lipid raft formation." (PMID 37996944, 2023). "The group with PLPP2 overexpression exhibited notably larger tumor volume and largest tumor area compared to the vector-control group." (PMID 37996944, 2023). "To further illustrate the potential of PLPP2 as a tumor marker, we employed a recombinant lentivirus to induce overexpression of PLPP2 in BEAS-2B and MLE-12 cells, which are normal lung epithelial cells." (PMID 37996944, 2023). "Overexpression of PLPP2 in LLC cells significantly enhanced tumor formation in mice." (PMID 37996944, 2023). "To assess the effects of PLPP2 on the malignant phenotypes of LUAD cells, we conducted mice tumor-bearing experiments and in vitro cellular experiments by knocking down PLPP2 and inhibiting lipid raft synthesis with MβCD, respectively." (PMID 37996944, 2023). "MβCD significantly mitigated the overexpression of PLPP2-induced excessive proliferation, characterized by high-positive staining of Ki-67 and PCNA in tumor tissues." (PMID 37996944, 2023). "Four genes, G6PD, APLP1, GCNT3, and PLPP2, were also over-expressed in advanced stage (III and IV) and high grade (3 and 4) ccRCC and tumor with necrosis (PADJ<0.05)." (PMID 30603059, 2018). "Additionally, the genes in the Light-Yellow module include SPDEF, ELAPOR1, C9orf152, PLPP2, and SCGB2A1 and may be involved in several biological processes including tumor immunity and epithelial cell differentiation." (PMID 39596419, 2024). "PLPP2 gene was over-expressed in tumor, but was not statistically significant (P = 0.07)." (PMID 30603059, 2018).
infection (1 paper, 2022). The state of being infected such as from the introduction of a foreign agent such as serum, vaccine, antigenic substance or organism. "In addition, genes related to glycerolipid metabolism (Plpp2), glycolysis metabolism (Pfkp), adipocyte differentiation (Rapgef4), nucleotide metabolism (Entpd3), serine catabolism (Shmt1), retinol metabolism (Akr1b10), and lipid-grading metabolism (Pla2g4f) were upregulated after EgPSC infection." (PMID 36713407, 2022).
neurodegenerative disease (1 paper, 2023). A disorder of the central nervous system characterized by gradual and progressive loss of neural tissue and neurologic function. "The GSEA results demonstrated that these 3 key genes (DLD, PLPP2, and PLAAT4) were all associated with neurodegenerative diseases, which supports the notion that the identification of these key genes was accurate to some extent." (PMID 37736681, 2023).
PLPP2 also shares sentences with these, for which no sentence is quoted: Alzheimer disease (1 paper); cholangiocarcinoma (1); colon adenocarcinoma (1); colorectal adenoma (1); colorectal cancer (1); Huntington disease (1); Immunodeficiency (1); lipid metabolism disorder (1); lung squamous cell carcinoma (1); pancreatic adenocarcinoma (1); paraganglioma (1); Parkinson disease (1); pheochromocytoma and (1); skin cutaneous melanoma (1).